IL1B (interleukin 1 beta)
Diseases named in the same sentence as IL1B in open-access papers (continued):
Sharing a sentence is not in itself a finding about the gene and the disease.
infection (continued). "Basic Protocol 2 details a primary, human co-culture system that consists of SARS-CoV-2-infected primary human airway epithelia (HAE) grown at an air-liquid interface (ALI) and primary human PBMCs, and how to observe IL-1β and IL-6 crosstalk between these cell populations during infection." (PMID 41949496, 2026). "Moreover, during such an acute host response towards infection, the IL-1β release was found to initiate the recruitment and activation of phagocytes to clear S. aureus." (PMID 40001363, 2025). "However, dual silencing of GSDMD and GSDME was required to reduce IL-1β secretion following Brazil/78 infection." (PMID 40481027, 2025). "Certain immune cells within vulnerable populations may generate TNF-α in response to external conditions and infection, IL-1β, IFN-α and IL-6, thereby promoting the production of IL-23 by dendritic cells." (PMID 40540498, 2025). "Nevertheless, infection of MH-S macrophages with the MtbΔctpA mutant resulted in the transcription or production of proinflammatory cytokines and microbicidal components essential for the control of Mtb during natural infection, such as IL-1β, IL-12, TNF-α, iNOS, and NADPH oxidase." (PMID 40002852, 2025). "Before infection, aging was associated with increased expression of inflammation-related markers (Il10, Tnfa, and Il1b) in VAT, but not in SCAT." (PMID 41145556, 2025). "Notably, NLRP3 was found to selectively drive IL‐1β secretion in P. aeruginosa‐infected neutrophils, thereby regulating the severity of infection." (PMID 40529614, 2025). "However, there were no significant changes in expression levels of the pro‐inflammatory cytokines, IL‐6 and IL‐1β, in either muscle following infection." (PMID 39871399, 2025). "Additionally, despite robust infection establishment in the presence of both pan-caspase (z-VAD) and caspase-1 (VX-765) inhibitors, IL-1β production was attenuated in THP1/PMA/NLRP1 macrophages compared to DMSO-treated infection control." (PMID 40920844, 2025). "BMDMs support ZIKV replication, and exhibit increased IL1β RNA and protein levels post-infection." (PMID 40688087, 2025). "Studies using longer exposure times or higher infection rates might favor the release of other DAMPs, which eventually results in activated IL-1β secretion." (PMID 41246354, 2025). "The pyroptosis-related genes NLRP3 and IL-1β were also significantly upregulated in response to infection, indicating the activation of inflammasomes and the subsequent release of pro-inflammatory cytokines that are crucial for the host’s defense against infection." (PMID 40727705, 2025). "In addition, the expression of pro-inflammatory cytokines, such as Il1b, Tnf and Il6, was also reduced in RBP4-deficient mice on day 3 post-infection, indicating a decrease inflammation." (PMID 41144502, 2025). "Neutrophils, immune cells essential to fight infections, accumulate in large numbers in CF airways and release neutrophil extracellular traps (NETs) into the airway lumen that deliver extracellular DNA, granule content and cytokines including IL-1β." (PMID 40791588, 2025). "However, in severe infections, excessive activation of the immune system leads to a major release of proinflammatory cytokines (e.g., IL-6, IL-1β, IFN-γ), shifting protective immune responses to harmful ones." (PMID 41012139, 2025). "Additionally, we observed significantly decreased Tnfα and Il1β at the end of the infection, suggesting that SP receptor antagonism reduced bacterial burden and pathology leading to lasting effects in the host after the pathogen was cleared." (PMID 39937862, 2025). "When inflammasomes identify pathogenic microorganisms and stress signals, they activate caspase-1, which cleaves IL-1β and IL-18 into their active forms to trigger a strong proinflammatory response that helps to remove pathogens by attracting immune cells to the infection site." (PMID 40331999, 2025).
infection (continued). "While infection with A. baumannii increased the expression of inflammasome-related genes, such as Nlrp3 (about 1.1) and Il1β (about 0.8) in the lungs of previously healthy mice, the transcript levels of these genes were lower in the two-hit mice (about 0.7 for Nlrp3 gene and about 0.6 for Il1β)." (PMID 40202049, 2025). "Additionally, a mouse infection model was established using P. aeruginosa PAO1 to investigate the impact of RmmLII on the production of inflammatory cytokines IL-1β, IL-6, and TNF-α, as well as mouse survival rates." (PMID 40170927, 2025). "Likewise, pro-IL-1β expression and caspase 1 were also enhanced in S. Typhimurium-infected sip62 BMDMs compared to siCtrl BMDMs at 6h post infection when autophagy is inhibited and p62 accumulates." (PMID 40276384, 2025). "The stimulatory activity of TcpC on IL-1β and TNFα secretion is remarkable, since bacterial numbers, which were identical between the strains at the beginning of the infection, were reduced Atc-dose dependently at the end of the culture period of 5 h due to induced TcpC expression." (PMID 41310197, 2025). "Oviedo-Boyso and colleagues reported that IL-1β and TNFα, when added to bovine endothelial cells before infection with S. aureus, increase their ability to eliminate intracellular S. aureus and S. epidermidis, thus remarking the role of IL-1β and TNFα in the interaction." (PMID 41425551, 2025). "While various factors, including host factors and different viral strains, can contribute to contrasting infection outcomes, evidence so far suggests that pyroptosis can lead to worse hMPV disease outcomes through IL-1β-mediated inflammation and increased hMPV replication in airway epithelial cells." (PMID 41011440, 2025). "Infection apparently increased the number of Il1β-producing cells." (PMID 40127923, 2025). "Additionally, in the immune response, pro-inflammatory factors such as IL-6 and IL-1β recruit immune cells to the infection or injury site to promote inflammation." (PMID 39670511, 2025). "Although it is important to note that GSDMD silencing also limited IL-1β release in response to HKx31 infection in a separable manner, suggesting that other lytic and non-lytic secretion mechanisms are in play in lung epithelial cells to promote damaging inflammation." (PMID 40481027, 2025). "Both infected groups showed increased IL-1β levels post-infection." (PMID 40453458, 2025). "Cytokine levels decreased for 6 of 9 assayed cytokines or the chemokine in the Chr7×3 AAB variant (IL-17a, IL-22, IL-5, IFN-γ, TNF-α, and IL-1β) and further decreased for all cytokines and the CXCL1 chemokine in the Chr7×3 ABB variant when compared to infection with Chr7×2 SC5314." (PMID 39896449, 2025). "At 3 h and 6 h post-infection, Il1b expression lost statistical significance, whereas Acod1 showed significant upregulation in L. major-infected macrophages in comparison to non-infected BMDMs at both time points (p-value = 0.0077 and p-value = 0.0121, respectively)." (PMID 40142422, 2025). "This discrepancy may be explained by the infection and the well-known IL-1β-mediated regulation of NOS2 expression via ERK1/2 and STAT1α signaling pathways." (PMID 41415272, 2025). "Finally, we analyzed by quantitative RT-PCR the expression of thepro-inflammatory cytokines il1b and tnfa, known tobe highly expressed upon Mab infection." (PMID 41020612, 2025). "Furthermore, IL-1β acts on the hypothalamus to induce fever, which is a common response to infection that helps inhibit the growth of pathogens." (PMID 39859545, 2025). "Notably, WT and NAIP-/- cells pretreated with glycine exhibited significantly decreased cell death and a small defect in IL-1β release following infection compared to infected cells treated with the vehicle control." (PMID 40162563, 2025).
infection (continued). "Cytokine levels decreased for 6 of 9 assayed cytokines or the chemokine in the Chr7x3 AAB variant (IL-17a, IL-22, IL-5, IFN-γ, TNF-α, and IL-1β) and further decreased for all cytokines and the CXCL1 chemokine in the Chr7x3 ABB variant when compared to infection with Chr7x2 SC5314." (PMID 40577316, 2025). "GrzmK also induces a pro-inflammatory immune response by stimulating the release of IL-1β, IL-6, and IL-8 by macrophages, fibroblasts, epithelial cells, and endothelial cells to take care of the infection by promoting immune cell infiltration and their pro-inflammatory actions." (PMID 41009359, 2025). "Similarly, both types of MaugOs supported OC43 virus infections, and the infection triggered significant IL-1β production." (PMID 40368896, 2025). "Moreover, in the fish experiment, OmTRIM25 and finTRIM2 were up-regulated in the gills two days post-infection (dpi), whereas IL-1β and TNF-α2 had a higher gene expression at four and six dpi, respectively." (PMID 41514764, 2025). "We investigated the effects of mPGES-1 inhibitors (MF63 and MK886) on the production of pro-inflammatory cytokines (TNF-α, IL-1β, and IL-6), the anti-inflammatory cytokine IL-10, and the chemokine IL-8 in macrophages infected with E. coli at a multiplicity of infection (MOI) of 5:1." (PMID 40666730, 2025). "The table below presents the mean values of the concentrations of the analyzed proinflammatory cytokines; TNF-α, IL-1β and IL-6 (expressed in picograms per milliliter [pg/mL]) ± standard deviation measured in patients with PCOS with infections caused by atypical pathogens and in the control groups." (PMID 40647668, 2025). "Furthermore, ΔsodA infection resulted in attenuated inflammatory responses, evidenced by lower expression of IL-1β, TNF-α, and NF-κB p65." (PMID 41030551, 2025). "Importantly, analysis of IAV responses at 24 h revealed that knockdown of GSDMD expression was sufficient to limit IL-1β secretion following HKx31 infection." (PMID 40481027, 2025). "In vertebrates, the interleukin-1β molecule (IL-1β) is among the most important proinflammatory cytokines and plays crucial roles in shaping injury progression, immunological challenges, and local and systemic responses to infection." (PMID 41594587, 2025). "Interleukin-1β (IL-1β) and interleukin-6 (IL-6) are chemotactic cytokines that amplify inflammation, activate neutrophils and macrophages, promote alveolar bone resorption and febrile responses, and play key roles in infection and tissue injury." (PMID 41354715, 2025). "When infection occurs, neutrophils are rapidly recruited from the peripheral circulation to the infection site under the action of various chemokines (such as IL‐8, IL‐1β, tumor necrosis factor [TNF], endotoxin, prostaglandins, and leukotrienes [LTs]) to exert their innate immunity." (PMID 40060194, 2025). "Indeed, pretreatment of stimulated PBMC with IL1B for 2 days resulted in a dose-dependent decrease in infection with the R5-tropic YU-2 virus as determined by the frequencies of sorted p24 + CD4+ T cells." (PMID 40442100, 2025). "The expression levels of IFN-γ, IFN-α, IL-1β, IL-6, and IL-12p40 mRNA were significantly increased, reaching their highest levels at 12 days post-infection (dpi), with fold changes of 18.49-, 28.39-, 36.98-, and 28.98-fold, respectively, before gradually declining thereafter." (PMID 41295722, 2025). "Notably, the infection-induced expression of Il10, Tnfa, and Il1b was significantly higher in aged mice compared to young mice." (PMID 41145556, 2025). "Our results indicate that, for infection with M. tuberculosis or M. kansasii, sensing of the infection by the non-canonical pathway is essential for host inflammasome responses, since caspase-4/5 are required for IL-1β release." (PMID 40272180, 2025). "IL‐1β is a key protein in the pro‐inflammatory response to infections." (PMID 41342328, 2025).
infection (continued). "Notably, in vivo infection experiments in mice confirmed that IL-1β significantly restricted SARS-CoV-2 spread in the lung epithelium." (PMID 39937682, 2025). "Furthermore, the expression of TLR4, IL-1β, IL-6, and IL-10 was up-regulated at 24 h post infection in the common carp (Cyprinus carpio) spleen in response to A. hydrophila." (PMID 40298788, 2025). "Tumor necrosis factor-α (TNF-α) is a pivotal early mediator that recruits inflammatory cells to sites of infection; it activates neutrophils and lymphocytes, modulates tissue metabolism, and stimulates the release of other cytokines (e.g., IL-6 and IL-1β), acting synergistically in pain signaling." (PMID 41354715, 2025). "VAP cases exhibited higher TNF-α levels and metabolic profiles indicative of anaerobic adaptation, while IL-1β elevations were primarily linked to mechanical ventilation rather than infection." (PMID 40611327, 2025). "Additionally, Mpro of SARS-CoV-2 blocks nuclear translocation of p65, a component of the NF-κB complex, upon IL-1β treatment or during infection with Sendai virus (SeV)." (PMID 39940968, 2025). "Besides analyzing ferroptosis-related protein markers, this cohort study also evaluated traditional biochemical indicators of infection, including IL-1β, IL-6, IL-8, IL-10, CXCL2, and TNF-α." (PMID 40264754, 2025). "Clinical isolates of P. aeruginosa from PwCF collected at the beginning of infection induce inflammasome signaling, cell death and expression of IL-1β in macrophages, however, chronic isolates displayed poor inflammasome activation and proinflammatory cytokine release." (PMID 40791588, 2025). "At 4 h of infection with M. kansasii and 24 h of infection with M. tuberculosis, the absence of caspase-4 and caspase-5 was associated with a complete absence of IL-1β release." (PMID 40272180, 2025). "As expected, SL1344 induced significant IL-1β cleavage during infection of THP-1 macrophages." (PMID 40560760, 2025). "The heightened vulnerability in females parallels recent epigenomic studies showing estrogen-mediated amplification of H. pylori-induced IL-1β production, while the age-independent effects contradict earlier assumptions that infection sequelae diminish with immune senescence." (PMID 41282285, 2025). "We have previously shown that infection with SARS-CoV-2 P21 causes increased production of a range of pro-inflammatory cytokines in the lungs of infected WT animals at multiple time points post-infection, including IL-1β, IL-18, IL-6, TNF, IFN-γ and others." (PMID 40016339, 2025). "miR-190a-3p/IL1B exhibited significant differential expression in both infection groups." (PMID 40725488, 2025). "Although there were similarities in disease amelioration compared to infected WT mice, loss of IL-1β caused a more profound drop in inflammatory cytokine levels at later time points during infection compared to the absence of its cognate receptor." (PMID 40016339, 2025). "Monocyte activation with palmitate for 18 h before infection (referred to as priming) with different SARS‐CoV‐2 variants (B1, Delta, Omicron) led to an increased viral load and elevated gene expression of IL‐6 and IL‐1β in all variants tested." (PMID 40265287, 2025). "Taken together, it appears that during an infection with CFT073ΔtcpC + pASK-IBA5plus-TcpC strain the ratio between the amount of TcpC and the number of bacteria present during the culture period is crucial for maximal stimulation of IL-1β secretion." (PMID 41310197, 2025). "This suggests that IL-1β production is a secondary response after the initial infection event." (PMID 40127923, 2025). "This increased secreted STC1 protein could inhibit macrophage chemotaxis to infected cells and also may inhibit IL‐1β secretion from macrophages to inhibit a pro‐inflammatory response to infection." (PMID 41342328, 2025).
infection (continued). "To understand how the ST74 population may be suppressing macrophage death at earlier stages of infection, we measured protein secretion of IL-1β via cytokine release and immunoblot assays at 9 hpi, respectively." (PMID 40560760, 2025). "After 90 min of infection, the levels of secreted IL-1β in cells infected with SP1450 reached 91.7% of the respective nigericin control, which was significantly higher than samples infected with SF370 (34.6%) and SP1380 (65.1%), and markedly higher than 5448-infected samples (71.3%)." (PMID 39688411, 2025). "Here, GSDME deficiency modestly reduced levels of IL-1β but not IL-18 in the airways following HKx31 infection, potentially due to differential regulation of the expression of these cytokines in vivo." (PMID 40481027, 2025). "For assessing the cytokine response, negative correlations were observed (Spearman test) between pre-infection levels of pro-inflammatory cytokines (IL-1β, TNF-α, IL-6) and viral loads in the moment of sacrifice in multiple organs, including the brain, lungs, and heart." (PMID 40969767, 2025). "Compared to FXIIf/f, FXII−/− mice exhibited markedly higher levels of IL-1β mRNA after infection." (PMID 40649792, 2025). "At the higher inoculum, WT and tlr4 mutant mice exhibited significantly increased levels of IL-1α, IFN-γ, TNF-α, MCP-1, IL-1β, IL-6, and IL-17A early during infection relative to the lower inoculum while levels dissipated by 7 dpi, consistent with bacterial clearance." (PMID 40817088, 2025). "Conversely, in young mice, infection led to reduced Il1b levels at 7 dpi." (PMID 41145556, 2025). "Interestingly, the IL-1β response on day 1 post-infection showed a moderate positive correlation with aggregate formation score." (PMID 40162896, 2025). "The levels of pro-inflammatory cytokines, such as tumor necrosis factor alpha (TNF-α), interleukin 6 (IL-6), and interleukin 1 beta (IL-1β), which drive chronic inflammation in plasma and lymph nodes, remain elevated from early infection stages and persist even in ART-treated individuals." (PMID 40704918, 2025). "Additionally, LINC02528+/– macrophages exhibited elevated IL-1β transcriptional levels at 12 h, 24 h and 48 h post-infection with Mtb compared to WT macrophages." (PMID 41433368, 2025). "Yptb WT infection induced higher TNFA and IL1B mRNA expression compared to ΔtkeA infection." (PMID 40365777, 2025). "Likewise, infection of bone marrow-derived dendritic cells (BMDCs) led to the processing of pro-IL-1β upon P. brasiliensis recognition, not only by caspase-1-dependent inflammasome responses, but also by caspase-8-dependent mechanisms." (PMID 41249509, 2025). "The extent to which Acanthamoeba CS and CL regulate autophagy and IL-1β secretion may vary based on tissue localization and infection stage." (PMID 40109888, 2025). "For example, a conjugated antibody that targets fungal β-glucan could facilitate the localized delivery of an inflammasome inhibitor, which would attenuate IL-1β secretion specifically at the infection site." (PMID 41304803, 2025). "In support of SP receptor regulation of specific gene expression profiles in response to enteric bacterial infection, Tnfa and Il1β expression induced by infection were significantly reduced by TACR1 antagonism 29 dpi compared to vehicle-treated and infected mice." (PMID 39937862, 2025). "In summary, mtROS are typically seen as an upstream factor that influences glycolytic pathways and the production of IL-1β in Mtb-infected macrophages, coordinating metabolic reprogramming and inflammatory responses to enhance the host’s immune defense against the infection." (PMID 41433368, 2025). "Thus, further in vivo studies are needed to assess the dynamic interplay between Acanthamoeba spp., autophagy, and IL-1β secretion in different infection models." (PMID 40109888, 2025).